IL25 (interleukin 25)
Diseases named in the same sentence as IL25 in open-access papers (continued):
Sharing a sentence is not in itself a finding about the gene and the disease.
food allergy (12 papers, 2013 to 2024). Gastrointestinal disturbances, skin eruptions, or shock due to allergic reactions to allergens in food. "Innate cytokines that drive type 2 immunity, namely TSLP, IL-33, and IL-25, have also been shown to be necessary for the development of food allergy in mouse models." (PMID 36880703, 2023). "In a mouse model of food allergy, neutralization of all Th2-driving cytokines IL-25, IL-33, and TSLP was necessary to suppress symptoms, but this was not performed in the context of OIT." (PMID 36880703, 2023). "In another model of ovalbumin-directed food allergy, IL-25 activated ILC2s in the gut to produce IL-5 and -13 and, in concert with activated Th2 cells, promoted anaphylaxis." (PMID 33488627, 2020). "Activation of the NF-ĸB signaling pathway and release of epithelium-derived IL-33, TSLP, and IL-25 are observed in airway epithelium during the initiation of type 2 immune response in respiratory mucosa and in food allergy." (PMID 31810340, 2019). "IL-25 stimulation, together with CD4+Th2 cells, that are induced after allergic sensitization, cause ILC2s to produce large amounts of IL-5 and IL-13, resulting in the development of food allergy in mice." (PMID 33333859, 2020). "Additionally, skin damage leading to alarmin (IL-33, TSLP, and IL-25) release can act as an innate stimulus for DC activation in mouse models of cutaneous allergy; this may mirror the skin barrier break down in people with eczema, who are more susceptible to food allergy." (PMID 33488627, 2020). "In murine models of food allergy, oral exposure to antigen and an adjuvant stimulates gut epithelial cells to express the innate pro-allergenic IL-33, IL-25, and thymic stromal lymphopoietin (TSLP), which contribute to the development of acute reactions to food and promotion of Th2 response." (PMID 31810340, 2019). "Our data are insufficient to make a conclusion on the nature of a IL-25 subgroup, but it can be speculated that these patients have a more severe type of food allergy." (PMID 24295226, 2013). "The existing evidence indicates that IL-33, IL-25 and TSLP induced by danger signals in tissues, are a key players in pathogenesis of epicutaneously induced food allergy 13,48]." (PMID 36904070, 2023). "The epithelial cell-derived cytokines IL-33, IL-25, and TSLP are central regulators of type 2 immunity, which promotes a wide array of allergic responses, including food allergies." (PMID 36429158, 2022). "Epithelial Type 2-inducing cytokines, such as IL-25, IL-33, and TSLP, are important drivers of inflammation in food allergy, however, most experimental studies have relied on whole body knockouts or systemic antibody-mediated neutralization in mice." (PMID 33365031, 2020). "In mice it was proven that only a cocktail of the three monoclonal antibodies against IL-25, IL-33, and TSLP can inhibit the development of food allergy in mice." (PMID 33333859, 2020). "A role for IL-25 in food allergy was proven in mice lacking IL-25 receptor that were more resistant to developing experimental IgE-mediated food allergy." (PMID 36904070, 2023). "Combined treatment with the antagonists of TSLP, IL-25 and IL-33 or with an inhibitor of pro-TH2 cytokine production might be able to suppress established human food allergy." (PMID 34301307, 2021). "In another study using a food allergy mouse model, blockade of IL-25, IL-33, or TSLP did not suppress established food allergies, and optimal food allergy suppression required treatment by combined blocking of all three cytokine signals." (PMID 32309281, 2020).
allergic rhinitis (10 papers, 2013 to 2025). Inflammation of the nasal mucous membranes caused by an IgE-mediated response to external allergens. "Airway ILC2s express far more ST2 than IL-17RB, and while both IL-33 and IL-25 are produced by nasal epithelial cells during HDM-induced allergic rhinitis, defects in eosinophil and goblet cell counts are seen only in IL-33−/− and not IL-25−/− mice." (PMID 41409758, 2025). "Studies on the levels of alarmins in patients with allergic rhinitis have shown that levels of IL-33, IL-25, and TSLP are significantly higher compared to healthy controls." (PMID 35406669, 2022). "The expression of IL-25 in the nasal mucosa and the concentration of IL-25 in the serum are positively correlated with the severity of AR, which can be used to judge the severity of allergic rhinitis." (PMID 30345318, 2018). "Therefore, we investigated the role of IL-25 in allergic rhinitis (AR) patients sensitized to HDM." (PMID 28912627, 2017). "However, the precise roles of IL-33 and IL-25 in house dust mite (HDM)-induced allergic rhinitis (AR) remain unclear." (PMID 24205109, 2013). "Airway epithelium plays an important role during the development of allergic rhinitis (AR), which is characterized by production of thymic stromal lymphopoietin (TSLP), interleukin 33 (IL-33), and interleukin 25 (IL-25)." (PMID 34899052, 2021). "Therefore, inhibitors related to IL-25 may be a new target for the treatment of allergic rhinitis." (PMID 30345318, 2018). "We previously demonstrated that IL-25 is produced by epithelial cells in the lungs and noses of mice during OVA-induced airway inflammation and HDM-induced allergic rhinitis, respectively." (PMID 30575775, 2018).
dermatitis (10 papers, 2016 to 2025). An inflammatory process affecting the skin. "IL-25 as another important alarmins to activate ILC2s has been suggested to play an essential role in driving IL-13 expression by skin ILC2s to mediate skin inflammation in mouse AD model, both in acute and chronic phase." (PMID 40236701, 2025). "In vitro study, IL-25 acts synergistically with T2 cytokines to inhibit filaggrin expression and aggravate skin inflammation." (PMID 40236701, 2025). "IL-25 and IL-33 are overexpressed in skin of patients with AD,16, 49, 50, 51 with TSLP overexpression associated with skin inflammation in mice." (PMID 26299987, 2016). "In addition, mast-cell-derived IL-25 promoted IL-1β production by dermal dendritic cells, which led to exacerbation of Th17-cell-mediated skin inflammation." (PMID 35874756, 2022). "Research on IL-25 led to just two results, which is not nearly enough to suggest any possible proposition but leads to a need for further studies in this sense, since IL-25 might play a role in the very early phases of this dermatosis." (PMID 34944487, 2021). "Hence, the IL-25 embargo may represent a promising strategy for targeting skin inflammation." (PMID 36834723, 2023). "MC903-induced dermatitis was dependent on thymic stromal lymphopoietin (TSLP), IL-25 and IL-33 in BALB/c mice, and on TSLP, but not IL-25 or IL-33, in C57BL/6 mice." (PMID 35874756, 2022).
rheumatoid arthritis (9 papers, 2015 to 2026). A chronic, systemic autoimmune disorder characterized by inflammation in the synovial membranes and articular surfaces. "IL-25, a new member of the IL-17 cytokine family, is involved in type 2 immunity initiation and has been associated with the pathogenesis of rheumatoid arthritis (RA)." (PMID 27812008, 2016). "Our data have shown that IFX therapy could downregulate Th1/Th17-associated proinflammatory cytokines and promote IL-25 production, consistent with previous work showing that serum level of IL-23 was significantly decreased in rheumatoid arthritis patients treated with IFX." (PMID 25873771, 2015). "IL-25, IL-6, and bioactive IL-17A were quantified in rheumatoid arthritis (RA) patient plasma." (PMID 28620392, 2017). "The present study aimed to evaluate the suppressive role of interleukin (IL)-25 in IL-22-induced osteoclastogenesis and receptor activator of nuclear factor κB ligand (RANKL) expression in rheumatoid arthritis (RA)." (PMID 32972460, 2020).
Arthritis (7 papers, 2016 to 2022). Inflammation of a joint. "Adoptive transfer of adequate ILC2s to arthritis models, in which the isolated cells were expanded in vitro through stimulation using cytokines such as IL-2, IL-7, IL-25, IL-33, and TSLP, mitigated experimental arthritis." (PMID 35163028, 2022). "Key type 2 cytokines, like interleukin (IL)-4 and IL-13, but also others such as IL-5, IL-9, IL-25, and IL-33, exert regulatory properties on arthritis, dampening inflammation and inducing resolution of joint swelling." (PMID 35163028, 2022). "In the mice arthritis model, type 2 collagen-induced arthritis, the level of IL-25 was elevated in the late stage of arthritis, while IL-17 was increased in the early stage." (PMID 35163028, 2022). "In another recent study, genetic deletion of ILC2s in mice resulted in exacerbated arthritis, whereas increasing ILC2 number by IL-25/IL-33 mini-circles or adoptive transfer significantly attenuated arthritis by affecting the initiation phase." (PMID 32051038, 2020). "Taken together, these results suggest that systemic administration of IL-25 attenuates arthritis onset and joint damage in CIA mice." (PMID 27812008, 2016). "The RA incidence and symptoms of arthritis in IL-25-treated mice were significantly reduced compared with PBS controls." (PMID 27812008, 2016). "It has been shown in a mouse model of collagen-induced arthritis that high expression of IL-25 is related to a regulatory mechanism in the presence of high levels of IL-17, and it has been found that IL-33 can intensify collagen-induced arthritis in experimental models." (PMID 34443554, 2021). "In addition, induction of ILC2 by administration of IL-25/IL-33 accelerated the resolution of K/BxN serum-induced arthritis in wild-type but not eosinophil-deficient ΔdblGATA mice." (PMID 34733292, 2021). "Thus, we next determined whether IL-25 can alleviate collagen-induced arthritis development in mice." (PMID 27812008, 2016). "In line with these human data, genetic deletion of ILC2 in mice aggravated K/BxN serum-induced arthritis whereas expansion of ILC2 by IL-25/IL-33 mini-circles or adoptive transfer of ILC2 from wild-type but not IL-4-/-IL-13-/- mice attenuated arthritis." (PMID 34733292, 2021).
atherosclerosis (7 papers, 2015 to 2024). A disease characterized by the build-up of fatty material and calcium deposition in the arterial wall resulting in partial or complete occlusion of the arterial lumen. "Atherosclerosis-prone apoE deficient mice were administrated IL-25 during both early (10–14 weeks of age) and late (21–25 weeks of age) stages of atherosclerosis to evaluate if IL-25 have any influence on the plaque initiation or plaque progression." (PMID 25629516, 2015). "Administration of 1 μg IL-25 per day for one week to atherosclerosis-prone apolipoprotein (apo)E deficient mice, had limited effect on the frequency of T cell populations, but resulted in a large expansion of ILC2s in the spleen." (PMID 25629516, 2015). "In this study we asked, whether administration of IL-25 to apoE deficient mice has any influence on atherosclerosis development." (PMID 25629516, 2015). "Additionally, administration of 1 μg IL-25 per day for 4 weeks in apoE deficient mice reduced atherosclerosis in the aorta both during initiation and progression of the disease." (PMID 25629516, 2015). "In recent years, the protective role of IL-25 in multiple diseases such as hepatic steatosis, atherosclerosis and kidney injury, has been determined." (PMID 38785317, 2024). "IL-25 was reported to inhibit the development of atherosclerosis by decreasing inflammation and oxidized LDL-specific antibodies." (PMID 34388961, 2021). "In the present study we attempted to investigate the direct effect of the IL25-induced splenic ILC2 (Lin−CD45+IL17RB+ICOS+IL7raint) population on the development of atherosclerosis by its adoptive transfer to hypercholesterolaemic apoE−/− mice." (PMID 31823769, 2019). "The purpose of this study was to evaluate if IL-25 has any influence on atherosclerosis development." (PMID 25629516, 2015). "The present findings demonstrate that IL-25 has a protective role in atherosclerosis mediated by innate responses, including ILC2 expansion, increased IL-5 secretion, B1a expansion and natural anti-PC IgM generation, rather than adaptive Th2 responses." (PMID 25629516, 2015). "The purpose of this study was to evaluate if IL-25 has any influence on atherosclerosis development in mice." (PMID 25629516, 2015). "We have previously indicated that genetic deletion of IL-25 in apoE−/− mice aggravates atherosclerosis in the aortic arch which was accompanied by increased levels of Th1 and Th17 responses as well as reduced frequencies of splenic ILC2s and plasma anti-PC IgM levels." (PMID 31823769, 2019). "Accordingly, the IL-25 treatment might have started too late in the atherosclerosis development to have any influence on the subvalvular plaques." (PMID 25629516, 2015). "We found an expansion of ILC2s in the spleen, increased levels of IL-5, elevated levels of plasma anti-phosphorylcholine (PC) natural IgM antibodies accompanied with reduced plaque area in the aorta of IL-25 treated mice, indicating that IL-25 protects against atherosclerosis development." (PMID 25629516, 2015). "In the present study, we attribute IL-25 with a protective role in atherosclerosis." (PMID 25629516, 2015). "IL-25 treatment significantly reduced initiation and progression of atherosclerosis development." (PMID 25629516, 2015). "However, in our IL-25 study we recorded decreased atherosclerosis burden in whole aortas while in the present study we could only detect decreased lipid content in the plaques of mice that received ILC2s." (PMID 31823769, 2019). "In the present study we attempt to further characterize the splenic IL25-induced ILC2 subset (Lin−CD45+IL17RB+ICOS+IL7raintermediate) as well as investigate the cells subset’s direct effect on atherosclerosis development through its adoptive transfer to atherosclerosis-prone apoE−/− mice." (PMID 31823769, 2019). "Thus, upregulation of IL-25 may alleviate atherosclerosis by reducing IL-22 expression." (PMID 34388961, 2021).
atherosclerosis (continued). "IL-25 as well as IL-33 induced by Th2 cells can promote the proliferation of ILC2 cells, and the activation of ILC2 cells in turn promotes the Th2 response, thereby reducing the burden of atherosclerosis." (PMID 39399488, 2024). "The aim of the current study is to characterize the interleukin 25 (IL25)-induced splenic ILC2 population (Lin−CD45+IL17RB+ICOS+IL7raintermediate) and address its direct role in experimental atherosclerosis by its adoptive transfer to hypercholesterolaemic apolipoprotein E deficient (apoE−/−) mice." (PMID 31823769, 2019).
colorectal cancer (7 papers, 2016 to 2025). A primary or metastatic malignant neoplasm that affects the colon or rectum. "In this study, we aimed to identify the effects of IL25 on decreasing colorectal cancer sensitivity to oxaliplatin by maintaining colorectal cancer stemness and the underlying mechanism." (PMID 35359953, 2022). "In the context of cancer, IL-33-activated ILC2 cells were found to bear anti-tumoral functions in lung cancer while IL-25-activated ILC2 cells promoted tumorigenesis in colorectal cancer." (PMID 37781372, 2023). "In a mouse model of colorectal cancer, IL-25 activation of ILC2 cells promoted intestinal tumorigenesis by recruiting and activating immunosuppressive M-MDSCs." (PMID 37781372, 2023). "Colorectal cancer (CRC) patients with higher tumor IL25 expression had reduced survival, and increased IL-25R-expressing tumor-resident ILC2s and myeloid-derived suppressor cells (MDSCs) associated with impaired anti-tumor responses." (PMID 35658010, 2022). "In this study, we show that IL25 is mainly expressed by cancer stem cells in the colorectal cancer microenvironment." (PMID 35359953, 2022). "Another target of IL-25, mmu-miR-135b-5p, has been shown to be up-regulated in UC and IBD-associated tumor tissues and is associated with colorectal cancer development and progression." (PMID 32779953, 2020). "In colorectal cancer models, IL-25 blockade increases tumor burden." (PMID 41041315, 2025). "In colorectal cancer (CRC), the IL-25—ILC2—MDSC axis suppresses anti-tumor immunity and fosters the formation of an immunosuppressive tumor microenvironment." (PMID 41041315, 2025). "In a mouse model for spontaneous colorectal cancer (CRC), the IL-25-ILC2 axis was found to be pro-tumoral, while inhibiting IL-25 signaling or ILC2 cells in an induced model of CRC led to an increased number of tumors." (PMID 37781372, 2023). "Targeting the IL25 signaling pathway may offer the potential to upgrade chemotherapy efficiency for colorectal cancer without damaging normal stem cells." (PMID 35359953, 2022). "However, the expression and biological role of IL25 in colorectal cancer is not properly understood." (PMID 35359953, 2022).